USP17L11 (ubiquitin specific peptidase 17 like family member 11)
Description:
Deubiquitinating enzyme that removes conjugated ubiquitin from specific proteins to regulate different cellular processes that may include cell proliferation, progression through the cell cycle, apoptosis, cell migration, and the cellular response to viral infection.
Tractability: No criterion of Open Targets' tractability assessment is met for any kind of drug.
Gene: Protein-coding gene on chromosome 4 (9,215,405 to 9,216,997, forward strand). Ensembl gene ENSG00000233136.
Subcellular location: Nucleus; Endoplasmic reticulum
Pathways (Reactome):
Metabolism of proteins: Ub-specific processing proteases
Gene Ontology:
Molecular function: cysteine-type deubiquitinase activity
Biological process: regulation of apoptotic process; protein deubiquitination
Cellular component: endoplasmic reticulum; nucleus
Homologues: Paralogues in human: USP17L18 (99% identical), USP17L20 (99% identical), USP17L19 (99% identical), USP17L22 (99% identical), USP17L17 (99% identical), USP17L24 (99% identical), USP17L25 (99% identical), USP17L26 (99% identical), USP17L27 (99% identical), USP17L28 (99% identical), USP17L29 (99% identical), USP17L30 (99% identical), and 59 more.